TIMP1 (TIMP metallopeptidase inhibitor 1)
Diseases named in the same sentence as TIMP1 in open-access papers (continued):
Sharing a sentence is not in itself a finding about the gene and the disease.
prostate tumor (4 papers, 2003 to 2022). "Since TIMP-1 overexpression has been associated with the blockade of metastasis in human prostate tumour xenograph model studies, we suggest that IL-10 may indirectly prevent tumour metastasis by this mechanism." (PMID 12771930, 2003). "As previously reported, both Ptenpc−/− and the Ptenpc−/−; Timp1−/− prostate tumors are characterized by the presence of both a proliferative and a senescent compartment, as detected by positivity to SA-β-Galactosidase (SA-β-Gal) staining and the expression of different senescence markers 6,20." (PMID 35449130, 2022). "Distinctly, IL-10 has been shown to stimulate TIMP-1 secretion and inhibit the secretion of MMP-2 and MMP-9 by prostate tumor cells." (PMID 33841538, 2020). "Another study showed that IL-10 stimulated TIMP-1 secretion and inhibition of MMP-2, 9 by prostate tumor cells." (PMID 33841538, 2020).
renal failure (4 papers, 2016 to 2022). "Relevant literature have shown that IL6, AKT1, VEGFA, FN1, TIMP1, ALB and TNF are associated with renal insufficiency." (PMID 36209090, 2022).
retinal degeneration (4 papers, 2018 to 2024). Degeneration of the retina. "We also envision that cytokine-induced aggregation of TIMP-1 in MGCs may be a novel mechanism involved in the inflammatory process in retinal degeneration, which may be associated with endoplasmic reticulum (ER) stress." (PMID 34270579, 2021). "In the present study using MIO-M1 culture system, we examined if MGCs express MMP-9 and TIMP-1 in response to proinflammatory conditions such as exposure to cytokines and oxidative stress that precipitates retinal degeneration." (PMID 34270579, 2021). "In contrast, more rod cells were found in TIMP1-treated rd1 retinas compared to the saline-treated retinas in the later stage of retinal degeneration." (PMID 29742163, 2018). "Here, we extend our initial rat studies to examine the potential of TIMP1 as a treatment in retinal degeneration by investigating neuroprotective effects in a classic mouse retinal degeneration model, rdPde6b-/- (rd1)." (PMID 29742163, 2018). "Our result showed that TIMP1 treatment prolongs some portion of outer segments of cones at advanced stages of retinal degeneration." (PMID 29742163, 2018). "A recent clinical trial and animal experiment also suggested that TIMP1 is significantly upregulated in retinal degeneration." (PMID 30405447, 2018). "Within the degenerating retina, TIMP-1 modulation may influence photoreceptor tissue migration and organization and can exert beneficial effects in retinal degeneration models." (PMID 38338800, 2024). "In the present study, we hypothesized that MGCs express endogenous MMP-9 and TIMP-1, the expression of which is altered in retinal remodeling during retinal degeneration." (PMID 34270579, 2021). "Additionally, TIMP1 is significantly upregulated in human and animal models with various ocular diseases including retinal degeneration, indicating that TIMP1 may have a critical role against intrinsic apoptotic cell death." (PMID 29742163, 2018).
scleroderma (4 papers, 2012 to 2025). Scleroderma is a rare autoimmune connective tissue disorder characterized by abnormal hardening of the skin and, sometimes, other organs. "The results obtained in the present study showed that the mean concentration of both TIMP-1 and TIMP-2 in the blood plasma of patients with scleroderma was higher, compared to the concentrations of these inhibitors in the blood plasma of healthy individuals." (PMID 32382564, 2020).
unstable angina (4 papers, 2012 to 2021). "Decreased TIMP‐2 plasma levels were detected in CAD and decreased plasma levels of both TIMP‐1 and TIMP‐2 in ACS and stable angina." (PMID 33381894, 2021). "This study evaluates the effect of IFN-γ on the MMPs/TIMP-1 ratio in cultured monocytes from 30 patients with stable coronary artery disease (CAD), 30 with unstable angina (UA) or non-ST-segment elevation myocardial infarction (NSTEMI), and 30 healthy blood donors." (PMID 23951304, 2013).
vascular dementia (4 papers, 2010 to 2023). A degenerative vascular disorder affecting the brain. "Decreased levels of TIMP-2 were found in serum of patients with frontotemporal dementia, and downregulated TIMP-1 was shown in patients with vascular dementia." (PMID 26538832, 2015).
vasculitis (4 papers, 2014 to 2026). "Transcript levels of TIMP1 were significantly higher in the HCV MC vasculitis cohort [1.80 ± 0.70 (NV), 4.8 ± 1.10 (HCV MC-Vasc), 2.80 ± 0.70 (HCV), 2.90 ± 1.00 (HIV/HCV); p = 0.03 between HCV MC-Vasc and HCV viremic]." (PMID 24904592, 2014). "Among the patients with MPA, those with motor neuropathy had significantly higher total Birmingham Vasculitis Activity Scores and serum levels of C-reactive protein (CRP), tissue inhibitor of metalloproteinase-1 (TIMP-1), and interleukin-6 than patients without motor neuropathy." (PMID 36362162, 2022).
acute lung injury (3 papers, 2022 to 2024). A condition of lung damage that is characterized by bilateral pulmonary infiltrates (pulmonary edema) rich in neutrophils, and in the absence of clinical heart failure. "Increased circulating tissue inhibitor of metalloproteinases‐1 (TIMP‐1) levels have been observed in patients with acute lung injury (ALI)." (PMID 39267201, 2024). "We also observed the dynamic equilibrium between MMP-9 and TIMP1, which has also been previously indited for acute lung injury." (PMID 36144218, 2022).
Aortic dissection (3 papers, 2016 to 2019). Aortic dissection refers to a tear in the intimal layer of the aorta causing a separation between the intima and the medial layers of the aorta. "Positive correlation between aortic dimensions and IL-6 or TIMP-1 was seen even after excluding patients with past aortic dissection, suggesting that associations between aortic dimensions and IL-6 or TIMP-1 are to some extent independent of former dissection or surgical manipulation." (PMID 30883599, 2019).
bacteremia (3 papers, 2018 to 2022). "As shown by our study, LIGHT is positively associated with TIMP-1 in bacterial sepsis, which may be related to its roles in the function of activated T cells and systemic inflammatory activation." (PMID 35203474, 2022). "High Pitt bacteremia scores were associated to higher MMP-8 (p<0.05) on day 28 but TIMP-1 level was not affected by the Pitt bacteremia score." (PMID 34043679, 2021). "Thus, the study cannot evaluate how MMP-8, TIMP-1 and MMP-8/TIMP-1 would perform in MRSA bacteremia." (PMID 34043679, 2021). "Future studies need to evaluate the pathogenetic role of MMP-8 and MMP-8/TIMP-1 in bacteremia which might open possibilities for pharmacological therapies to control their activation in bacteremia." (PMID 34043679, 2021). "In bacterial sepsis, LIGHT was positively correlated with TIMP-1, PAI-1, and TNFR2." (PMID 35203474, 2022). "First, we included only MS-SAB patients and MMP-8 and TIMP-1 concentrations were measured in relation to bacteremia onset regardless of severity of illness, PITT bacteremia score or ICU admission." (PMID 34043679, 2021). "Using unsupervised hierarchical clustering, we found that TNFα, CCL4, E-selectin, VCAM-1, ICAM-1, and TIMP-1 could be used to discriminate between patients with and those without bacteremia." (PMID 29681903, 2018). "In our study, we found six of the soluble mediators analyzed that differentiated between patients with and without bacteremia: TNF-α, CCL4, TIMP-1, VCAM-1, ICAM-1, and E-selectin." (PMID 29681903, 2018).
bronchiectasis (3 papers, 2012 to 2025). Segmental, irreversible dilation of the bronchial tree resulting in the accumulation of secretions which leads to obstruction. "Several reports have demonstrated that the MMP-9/TIMP-1 ratio is associated with the development of some diseases in newborn infants, including bronchiectasis and lung infection." (PMID 33263620, 2020). "In the same study, whereas levels of MMP-8 and MMP-9 were increased in bronchiectasis, their primary inhibitor TIMP-1 was not, indicating a protease-antiprotease imbalance." (PMID 40174958, 2025).
cardiac interstitial fibrosis (3 papers, 2017 to 2025). "TIMP-1 - together with TIMP-2 - is correlated to the development of cardiac interstitial fibrosis, possibly mediating CD63-Integrin β1 interaction." (PMID 41467913, 2025). "More importantly, renalase treatment significantly alleviates cardiac interstitial fibrosis, followed by the increased cardiac expression of MMP-1, lower expression of TIMP-1, and TGF-β, and decreased phosphorylated ERK 1/2 levels." (PMID 35711341, 2022).
carotid atherosclerosis (3 papers, 2015 to 2024). A thickening and loss of elasticity of the walls of carotid arteries that occur with formation of atherosclerotic plaques. "One of the most important findings of our study was the graded elevation of MMPs and TIMP-1 along groups divided according to the degree of carotid atherosclerosis." (PMID 37759829, 2023). "Furthermore, the MMP-9/TIMP-1 ratio has been proposed as a stronger independent predictor of coronary and carotid atherosclerosis." (PMID 37759829, 2023). "Besides CRP, novel biomarkers like matrix metalloproteinases (MMPs) 3,7, and 9 and the tissue inhibitors of metalloproteinase (TIMP)-1 are elevated in those with carotid atherosclerosis, and the elevation of those biomarkers parallel with the percentage of carotid artery stenosis." (PMID 38248862, 2024). "In the present study, patients requiring carotid revascularization appeared with higher levels of CAVI, MMP-3, MMP-7 MMP-9, and TIMP-1 compared to patients with carotid atherosclerosis under conservative treatment or controls without carotid atherosclerosis." (PMID 37759829, 2023). "In conclusion, patients with established carotid atherosclerosis presented with exaggerated CAVI, MMP-3, MMP-7 MMP-9, and TIMP-1 levels compared to individuals without carotid atherosclerotic plaques." (PMID 37759829, 2023).
chronic hepatitis (3 papers, 2004 to 2021). An active inflammatory process affecting the liver for more than six months. "Moreover, serum MMP-9 levels decrease as chronic hepatitis progresses to cirrhosis, while TIMP-1 levels increase along with an increase of the degree of fibrosis (r = 0.73, P < 0.001)." (PMID 21849046, 2011). "A recent study of the relationship between serum MMP-9, TIMP-1 and fibrosis in 50 patients with various chronic liver disease showed that serum levels of MMP-9 in chronic hepatitis patients were low as compared to the controls (P < 0.05)." (PMID 21849046, 2011).
chronic hepatitis B (3 papers, 2013 to 2025). "MMP-9/TIMP-1 complex was reported to be serum marker for fibrosis in children with chronic hepatitis B." (PMID 23672427, 2013).
chronic rhinosinusitis (3 papers, 2016 to 2021). Chronic form of sinusitis. "S. aureus has been shown to induce the tissue remodeling factors MMP2, MMP9, and TIMP1 in mucosal explants from chronic rhinosinusitis (CRS) patients." (PMID 28083514, 2016).
colon adenocarcinoma (3 papers, 2023 to 2025). "Compared with tumor adjacent tissues, EEF1A2, PBK and TIMP1 showed significant upregulation in colon adenocarcinoma, while ATP2A3, CDC25C, MMP3 and NAT1 showed significant downregulation." (PMID 37626132, 2023). "TIMP1 was significantly overexpressed in both colon adenocarcinoma (COAD) and rectal adenocarcinoma (READ) samples compared to adjacent normal tissues." (PMID 41511313, 2025).
cutaneous melanoma (3 papers, 2015 to 2023). A primary melanoma arising from atypical melanocytes in the skin. "The aim of the study was to define clinical utility of serum biomarkers: VEGF, MMP-2, MMP-9, TIMP-1, and YKL-40 in patients with skin melanoma at locoregional stage." (PMID 26002577, 2015). "In the presented study, we have evaluated a clinical utility of the concentrations of VEGF, MMP-2, MMP-9, TIMP-1, and YKL-40 in serum of patients with skin melanoma at locoregional disease." (PMID 26002577, 2015).
cyst (3 papers, 2018 to 2024). A sac-like closed membranous structure that may be empty or contain fluid or amorphous material. "Abundance of TIMP1 mRNA remained constant in preovulatory follicles and then sharply increased in both cyst groups." (PMID 37173342, 2023). "TIMP-1, a metalloproteinase inhibitor, is involved in extracellular matrix remodeling which is particularly intense in ovary during follicular development and cyst formation and in endometrium during dynamic cyclic changes across the menstrual cycle." (PMID 38341605, 2024). "Studies of other preneoplastic lesion such as IPMN and other cystic precursor lesions of the pancreas identify the proteins TIMP1 in plasma, mucin-5AC, mucin-2, cyst-fluid carcinoembryonic antigen and prostate stem-cell antigen in cyst fluids as potential protein biomarkers." (PMID 29865155, 2018). "However, we did not observe changes in expression of MMP2 and TIMP1 protein in follicular and cyst walls." (PMID 37173342, 2023).
demyelinating disease (3 papers, 2011 to 2016). A broad group of disorders that affect the myelin sheaths that cover the neurons. "However, the precise function of TIMP1 in demyelinating diseases is not known in detail, yet an impairment of lesion progression and myelin loss was suggested." (PMID 27441688, 2016). "Coincidently, analysis of TIMP-1 expression in acute demyelinating diseases that also show remyelination has shown robust expression of TIMP-1, whereas cerebrospinal levels of TIMP-1 across multiple clinical phenotypes of MS indicate no induction of TIMP-1 in this chronic inflammatory disease." (PMID 24961523, 2013).
esophageal cancer (3 papers, 2016 to 2025). A primary or metastatic malignant neoplasm involving the esophagus. "High levels of TIMP1 in serum are associated with disease progression and poorer prognosis in esophageal cancer (EC) patients." (PMID 40244296, 2025).
gastric ulcer (3 papers, 2010 to 2022). An ulcerated lesion in the mucosal surface of the stomach. "H. pylori-infected gastric ulcers had even higher MMP-7, MMP-9, and TIMP-1 expressions in epithelial cells than NSAID-related gastric ulcers (P < 0.05)." (PMID 22645431, 2012). "The results show stronger patterns of MMP-9 and TIMP-1 expression in H. pylori-infected gastric ulcer tissues." (PMID 22645431, 2012). "In patients with the two combined factors, gastric ulcers expressed similar proportions of antral ulcers and MMP-7 and MMP-9 intensities to NSAID-related gastric ulcers, but lower MMP-9 and TIMP-1 than H. pylori-infected gastric ulcers (P < 0.05)." (PMID 22645431, 2012). "By comparing gastric ulcer and nonulcer tissues within the same individual, this study is highly original in revealing how MMP-3, -7, and -9 and TIMP-1 expressions are upregulated in gastric ulcers induced by H. pylori infection and NSAID use, respectively (P < 0.05)." (PMID 22645431, 2012). "This study demonstrates that MMP-3, -7 and -9 and TIMP-1 may play a potential role in gastric ulcer formation or the healing process." (PMID 22645431, 2012). "by working on 126 gastric ulcer patients showed that H. pylori-infected gastric ulcers had even higher MMP-7, MMP-9, and TIMP-1 expressions in epithelial cells compared to NSAID-related gastric ulcers." (PMID 35832384, 2022). "Over superficial epithelium of gastric ulcer tissues, MMP-7, MMP-9, and TIMP-1 expressions were significantly lower in the NSAID-related group than in the H. pylori-infected group (P < 0.05)." (PMID 22645431, 2012). "Due to different expressions of MMPs and TIMP-1 between H. pylori-infected and NSAID-related gastric ulcers, cut-off values of MMPs and TIMP-1 have been measured to discriminate the possible characteristics: H. pylori infection or NSAID use?" (PMID 22645431, 2012). "We proposed that inflammatory cells of gastric ulcers participate vigorously in the healing process and upregulate MMP-3 and TIMP-1 strongly either in H. pylori infection or in the other two NSAID-use groups with or without H. pylori infection." (PMID 22645431, 2012). "The findings indicate that H. pylori-infected gastric ulcers express higher MMP-7, MMP-9, and TIMP-1 compared to NSAID-related ulcers." (PMID 22645431, 2012). "MMP-3, MMP-9, and TIMP-1 expressions over inflammatory cells of the gastric ulcer lamina propria were also higher than in nonulcer tissues (P < 0.001)." (PMID 22645431, 2012). "MMP-7, MMP-9, and TIMP-1 expressions over the superficial epithelium of gastric ulcer tissues were higher than in nonulcer tissues (P < 0.05)." (PMID 22645431, 2012). "Over inflammatory cells of the gastric ulcer lamina propria, only MMP-9 expression (not MMP-3 and TIMP-1) was significantly higher in the H. pylori-infected group than in the other two NSAID-use groups with or without H. pylori infection (P < 0.001)." (PMID 22645431, 2012). "Moreover, in the H. pylori-infected group, MMP-9 and TIMP-1 expressions over the superficial epithelium and MMP-9 expression over inflammatory cells of the lamina propria of gastric ulcer tissues were higher than in nonulcer tissues, respectively." (PMID 22645431, 2012).
hepatitis C (3 papers, 2021 to 2025). "TIMP1 is a natural inhibitor of matrix metalloproteinases (MMPs), and increased LPS stimulation of macrophages during hepatitis C virus infection can lead to MMP/TIMP1 imbalance." (PMID 39115879, 2024). "Levels of Timp1 correlate with fibrosis, and several groups have investigated the use of TIMP1 levels as a biomarker for fibrosis in hepatitis C patients." (PMID 34609282, 2021).
infertile (3 papers, 2015 to 2024). "In infertile patients, an increase in the follicular TIMP-1, but not TIMP-2, level was detected compared with that in the normally ovulating control group." (PMID 26337061, 2015).
Kawasaki disease (3 papers, 2021 to 2026). A rare inflammatory disease characterized by an acute febrile, systemic, self-limiting, medium-vessel vasculitis primarily affecting children. "Interestingly, elevated plasma levels of MMP-9, TIMP-1, and VEGF have also been found in the acute phase of Kawasaki disease, but not later, even in the presence of persistent coronary aneurysms." (PMID 34572455, 2021).
kidney (3 papers, 2019 to 2025). "Furthermore, diminished CXCL-10 and renin, as well as non-significant trends towards decreased biomarker concentrations for KIM-1, TIMP-1, and osteopontin were noted after CEF and PTX treatment, suggesting that addition of PTX to antibiotics may reduce acute kidney injury during neonatal sepsis." (PMID 39963236, 2024).
knee osteoarthritis (3 papers, 2014 to 2021). "Western blots were evaluated for differences in MMP-13, TIMP-1, NF-κB, IκB-β, and COL2A1 protein expression among the groups of rats with MIA-induced knee osteoarthritis." (PMID 28594958, 2017).